CSF1R (colony stimulating factor 1 receptor)
Diseases named in the same sentence as CSF1R in open-access papers (continued):
Sharing a sentence is not in itself a finding about the gene and the disease.
tumor (continued). "This cytokine binds to colony stimulating factor 1 receptor (CSF-1R) in the monocytes, directing their transformation toward the M2 phenotype and stimulating the secretion of anti-inflammatory, tumor-promoting factors IL-10 and TGF-β." (PMID 32477352, 2020). "Immunohistochemical results showed that CSF1R was expressed not only on the surface of macrophages, but also in tumor cells with high abundance." (PMID 32850346, 2020). "Macrophages in tumor-infiltrating areas can selectively ignore the presence of tumor cells by highly expressing CSF1R." (PMID 32724427, 2020). "Two of the most studied therapeutic strategies to deplete TAMs from the tumor microenvironment are the inhibition of CSF-1/CSF-1R signaling and the use of liposomes containing clodronate." (PMID 32326073, 2020). "Compared to anti-CSF-1R blocking antibody causing general TAM depletion, specific depletion of CD163+ TAMs was shown to be a more efficient inhibitor of tumor growth." (PMID 32752088, 2020). "The peritumoral liver tissue, which possessed of abundant CSF-1R, plays an opposite role in anti-tumor effect by providing a fertile environment for metastasis." (PMID 32760707, 2020). "Several studies show that blocking CSF-1/CSF-1R inhibited immunosuppressive macrophage polarization, reduced tumor cell proliferation, and promoted apoptosis, therefore suppressing tumor progression and prolonged life survival." (PMID 33251232, 2020). "Some trials utilizing monoclonal antibodies directed at CSF-1/CSF1R in adults exhibited limited anti-tumor activity (NCT01346358)." (PMID 33381449, 2020). "Supramolecular nanoparticles were used to inhibit colony-stimulating factor 1 receptor (CSF1R) and MAPK signaling and to further block the pro-tumorigenic phenotypes of tumor-associated macrophages." (PMID 31979325, 2020). "Next, the potent dual inhibitor—namely, 3D185, which targets FGFR1-3 and colony stimulating factor 1 receptor (CSF1R)—showed promising anti-tumor effects in FGFR-dependent and macrophage-dominant cancer models." (PMID 33081025, 2020). "After CSF1R inhibition, TAMs lose M2 polarization and show enhanced phagocytosis, providing a molecular corollary for their impaired tumor-promoting functions." (PMID 32000794, 2020). "Surprisingly, it is found that a large number of PMN-MDSC are recruited in tumor tissues after the treatment of CSF1R inhibitors with mice." (PMID 33224886, 2020). "It is worth noting that CSF1R inhibitor combined with CXCR2 antagonist intervention can block PMN-MDSC infiltration of tumor tissues, and has a strong tumor treatment effect." (PMID 33224886, 2020). "In CSF1R high-expressed group, higher immune scores and low tumor purity reflected the presence of immunoreactive gene expression subtypes." (PMID 32850346, 2020). "The decrease of CSF1R amounts with the triple treatment argues strongly for a reduction in tumor growth since the CSF1/CSF1R pathway exerts an autocrine proliferation loop in RCC and CSF1R is indicative of poor prognosis." (PMID 31938054, 2020). "The first and most widely used therapeutic macrophage-based strategy has been TAM depletion from tumor sites via the inhibition of colony stimulating factor-1/colony stimulating factor-1 receptor (CSF-1/CSF-1R) and CCL2/CCR2 inhibition." (PMID 32575899, 2020). "A recent study reported that CSF‐1R inhibitors exhibited anti‐tumour activity in AML by blocking paracrine signals from support cells." (PMID 33037771, 2020). "The immunofluorescence analysis provided evidence of effective reduction in macrophage density within the tumor as a result of the CSF1R inhibition." (PMID 31420495, 2020). "Lower methylation was accompanied by higher expression, indicating that there is a regulatory relationship between CSF1R hypomethylation in ANTs and tumor progression." (PMID 32724427, 2020).
tumor (continued). "It was reported that both small molecular inhibitors and antibodies targeting either CCL2/CCR2 or CSF-1/CSF-1R signaling axis obviously inhibited the mobilization of monocytes and macrophages accumulation in tumor sites." (PMID 31300030, 2019). "Even if no real response was achieved in vivo with monotherapy, combination strategies, in particular anti-CSF-1R/chemotherapy, showed a good tumor regression in patients." (PMID 31547627, 2019). "In a preclinical breast cancer model, anti-mouse CSF-1R antibodies were shown to deplete macrophages and to reduce tumor size." (PMID 31547627, 2019). "Therapeutic strategies targeting TAMs (such as CSF-1R inhibitors) were shown to be effective in syngeneic subcutaneous tumor models, but only in combination with immune stimulation or checkpoint blockade." (PMID 31681563, 2019). "A few studies reported that prolonged CSF-1R inhibition leads to an acquired resistance and tumor recurrence through activation of the PI3K pathway; the combination of PI3K blockade with CSF-1R inhibition prolonged survival in pre-clinical models." (PMID 31878087, 2019). "Other variants detected in this tumor, such as those inFGFR3,PDGFRA,KDR (c.1416A>T),CSF1R,EGFR,RET,HRAS,PIK3CA,FLT3 (c.1310-3T>C), andSMAD4, are benign." (PMID 32612806, 2019). "CSF-1R inhibition and its anti-tumor effects are not limited to solid tumor subtypes, but have also been appreciated in hematologic malignancies, where CSF-1R expressing macrophages within the TME stimulate tumor survival." (PMID 31439034, 2019). "Current efforts are aimed at combining CSF1R inhibitors with immunotherapy to potentiate and enhance tumor immunity." (PMID 31552020, 2019). "The inhibition of CSF-1 signaling using anti-CSF-1R neutralizing antibodies or small molecule inhibitors has been used to decrease infiltration of TAMs and MDSCs and consequently inhibit tumor progression and metastasis." (PMID 30781344, 2019). "First, digitized images of paraffin-embedded whole axial cross-sections of the tumor collected at CSF1R trial endpoints were analyzed by counting all TAMs according to their CD68 staining to measure general response to the CSF1R inhibitor." (PMID 30696910, 2019). "Preclinical investigations of PLX-3397, BLZ945 and ARRY-382 have paved the way for clinical studies of CSF-1R inhibition via small molecules and mABs in diverse tumor types from GBM to pancreatic, ovarian and colorectal cancers." (PMID 31439034, 2019). "To confirm our findings obtained in the ex vivo experiments, we decided to use alternative methods to attempt to reduce macrophage number in tumours by using clodronate liposomes or inhibition of CSF1R." (PMID 31160587, 2019). "We previously reported in classical Hodgkin Lymphoma (cHL) that a member of the THE1B class of LTR elements acted as a promoter for the proto-oncogene and growth factor receptor gene CSF1R and that expression of this gene is required for cHL tumour survival." (PMID 30546079, 2019). "Researchers found that administration of RG7155 significantly lowered the amount of CSF-1R expressing TAMs in on-treatment biopsies from tumor lesions." (PMID 31300030, 2019). "The enhanced anti-tumoral effect of CD8+ T cells as consequence of pharmacological inhibition of CSF-1/CSF-1R axis has also been exploited for combinational therapy with ICBs, especially for tumours resistant to single-agent therapy." (PMID 31331034, 2019). "These novel therapeutic strategies are mainly focused on inhibitors of CSF-1 or CSF-1R alone or combined with other therapeutic agents targeting tumor cells." (PMID 30781344, 2019). "The downstream effects of CSF-1/CSF-1R blockade create an environment with decreased immune suppression and increased interferon response, impeding tumor growth." (PMID 31439034, 2019). "In tumor cells, colony stimulating factor 1 receptor (CSF-1R) signaling can mediate the polarization status of TAMs." (PMID 31450627, 2019).
tumor (continued). "Other studies have reported on the ability of CSF-1R inhibition alone or in combination with other therapies to induce TAM reprogramming towards an anti-tumor M1 phenotype (see Section 4.2.4)." (PMID 31878087, 2019). "They found CSF1R inhibitor combined with irradiation suppresses tumor growth more effectively relative to irradiation alone." (PMID 31629410, 2019). "Macrophage depletion by CSF-1R blockade with small molecule inhibitors also showed increased infiltration of CD8+ cytotoxic T cells in the tumor and improved response to therapies in murine models of breast, prostate, and cervical tumors." (PMID 31878087, 2019). "Given that bone marrow-derived macrophages (BDMs) are recruited to the tumor by chemokine (C–C motif) ligand 2/CCL receptor 2 (CCL2/CCLR2) or colony-stimulating factor-1 (CSF-1)/CSF-1R axis, inhibitors targeting these ligands and receptors have been developed." (PMID 30823602, 2019). "The block in CSF1 signalling caused CAFs to secrete the PMN-MDSC chemokine, C–X–C Motif Chemokine Ligand 1 (Cxc11); CAFs were therefore able to neutralise the anti-tumour effect of the CSF1R inhibitor." (PMID 31289350, 2019). "For example, we have shown that a macrophage-depletion strategy through CSF1R inhibition, which by itself has a minor effect on the tumor growth, also improved the efficacy of an anti-PD-1 treatment." (PMID 31354719, 2019). "CSF-1R blockade leads to the alteration of macrophage polarisation in the TME, which shows lower myeloid cell content associated with a certain degree of tumour regression in preclinical animal models." (PMID 30413827, 2019). "Neutralizing anti–CSF-1R and anti–CSF-1 antibodies, or small-molecule inhibitors of CSF-1R, not only left the tumor growth unaffected but actually increased spontaneous metastasis." (PMID 31406165, 2019). "In this model, CSF-1/CSF-1R targeting resulted in increased expression of immune checkpoint molecule on tumour cells, including PD-L1 and CTLA-4, thus resulting in only modest increase of CD8+ T cell cytotoxicity." (PMID 31331034, 2019). "A preclinical study found that PLX3397, a CSF-1 receptor (CSF-1R) inhibitor, showed robust anti-tumor effects in xenograft HCC models, and the effects of sorafenib were enhanced when combined with macrophage-depleting drugs." (PMID 31655607, 2019). "In glioblastoma tumor-bearing mice, TAM depletion by CSF-1R monotherapy induced tumor reduction and increased survival." (PMID 31020037, 2019). "Several clinical trials of CSF-1/CSF-1R inhibitors have been performed or are still open in different tumor types." (PMID 31799182, 2019). "3D185, which simultaneously targets FGFR and CSF-1R, is expected to both inhibit tumor cells and remodel the tumor microenvironment to synergistically antagonize tumors and delay the development of resistance to FGFR inhibitors alone." (PMID 31438996, 2019). "Previous studies have demonstrated that TAM homeostasis requires CSF1R signaling where antibody blockade of CSF1R dramatically decreased TAM tumor content." (PMID 31552020, 2019). "It is important to highlight that the tumor growth reduced more than 90% when CSF1R blockade was combined with either anti-CTLA-4 or anti-PD-1 compared to the mice treated only with anti-CTLA-4 or anti-PD-1 alone." (PMID 30987642, 2019). "CSF-1R inhibitor GW2580 combined with an anti-VEGFR-2 antibody synergistically inhibits tumor proliferation and hampers tumor angiogenesis." (PMID 31695804, 2019). "Compensatory effects and enhanced tumor progression in response to CSF-1R inhibition has been recently attributed to increased granulocyte recruitment into tumors." (PMID 31878087, 2019). "The authors used a monoclonal antibody to block CSF-1R signaling, required for macrophage development and infiltration into tumor tissues." (PMID 31370273, 2019). "Studies have shown that a paracrine loop in CSF-1/CSF-1R signaling between TAMs and tumor cells is required in the tumor microenvironment." (PMID 31565097, 2019).
tumor (continued). "In cervical and mammary carcinoma mouse models, the depletion of TAMs, obtained by means of a highly selective CSF1R inhibitor, resulted in the arrest and delay of tumor growth, respectively." (PMID 29973487, 2018). "In this regard, it is noted that the c-Kit inhibitor imatinib inhibited breast stromal fibroblasts and reduced tumor growth, and that c-Kit/CSF1R inhibitors target tumor-promoting M2 macrophages in the TME of solid tumors." (PMID 29487713, 2018). "Here, we show that CSF1R inhibition produces both a vastly different phenotype but also different mechanistic consequences in terms of inhibiting growth of the primary tumor and relieving T cell suppression." (PMID 29719257, 2018). "The anti-tumor efficacy of anti-CSF-1R antibody appears to be partially achieved by its role in converting PD-1+ exhausted T-cells into CD137+ activated T-cells in the PDAC tumors." (PMID 30424804, 2018). "We find that, in a set of transplant and spontaneous cancer models, tumor cells secrete the cytokine CSF-1, which induces the NKG2D ligand RAE-1δ on tumor-associated macrophages via a CSF-1R-PI3Kα-dependent signaling pathway." (PMID 29757143, 2018). "As a receptor tyrosine kinase, CSF1R is an attractive therapeutic target, considering the tumor-permissive and immunosuppressive characteristics of CSF1R-expressing TAMs." (PMID 30065206, 2018). "Tissues were stained with antibodies against CSF1R, F4/80 to define macrophages, and E-cadherin to identify epithelial tumor cells." (PMID 29719257, 2018). "CSF1 is a key cytokine responsible for promoting M2 polarization through CSF1 receptor (CSF1R)-mediated signaling and CSF1R blockade in tumor models led to repolarizing of TAMs to the M1 phenotype." (PMID 30558196, 2018). "Here, we show that by removing one element of this stroma, CSF1R positive macrophages, many of the elements of the tumor stroma can be changed in a way that is beneficial for therapy." (PMID 29719257, 2018). "This work also confirmed the involvement of the EGF and CSF-1 paracrine loop in tumor cell migratory streaming by using erlotinib to block the EGFR on tumor cells or by using CSF1R antibodies to block the CSF1R on macrophages." (PMID 29599778, 2018). "Treatment of tumor‐bearing mice with CSF1R blockade did result in enhanced effector T‐cell tumor infiltration and reduced tumor growth." (PMID 30003190, 2018). "Targeting of tumor-associated macrophages with anti-CSF-1R reduced their infiltration, and when used in combination with anti-PD-1 or anti-CTLA-4, enhanced tumor regression." (PMID 29968076, 2018). "TAMs occupy 50% of the tumor volume and provides paracrine signals via CSF-1/CSF-1R axis, which promotes tumor progression." (PMID 30352606, 2018). "Following treatment with CSF1R blockade by a CSF1R tyrosine kinase inhibitor tumor, infiltrating macrophages and MDSC were depleted." (PMID 30003190, 2018). "In many malignancies, the tumor microenvironment includes CSF1R-expressing supportive monocyte/macrophages that promote tumor cell survival." (PMID 29872489, 2018). "PDAC tumors often express high levels of CSF-1 compared to normal tissue, and CSF-1R can be detected in the tumor stroma." (PMID 30424804, 2018). "In preclinical models of PDAC, anti-PD1 and anti-CTLA4 antagonists showed limited efficacy as monotherapies to restrain tumor growth, but the use of these agents in combination with CSF1R blockade resulted in tumor regression." (PMID 29594035, 2018). "Since no obvious characteristics of the CLL patient specimens readily co-segregated with CSF1R sensitivity, we examined the contribution of tumor-extrinsic factors." (PMID 29872489, 2018). "Recent progress in cancer immunology research has unveiled critical roles for colony stimulating factor 1 receptor (CSF1R) in multiple aspects of the tumor microenvironment." (PMID 29323162, 2018). "The efficacy of CSF1R inhibition, and its capacity to deplete TAMs seems to vary depending upon tumor type and tissue." (PMID 29946544, 2018).
tumor (continued). "CSF-1R blockade by a competitive inhibitor significantly delayed tumor growth in murine xenograft models." (PMID 30410942, 2018). "The inhibition of CCL2/C–C chemokine receptor type 2 or CSF1/CSF1-R pathways by several methods was shown to efficiently induce tumor regression." (PMID 28769933, 2017). "The key findings from our study are a decrease in tumor burden, ascites, and macrophage content when a CSF1R inhibitor is combined with anti-VEGF therapy in the setting of adaptive resistance." (PMID 29228548, 2017). "Many studies have demonstrated a relationship between the abnormal expression of CSF-1/CSF-1R and tumor development." (PMID 29228668, 2017). "Another newly discovered cytokine IL-34 expressed by osteosarcoma cells sharing CSF-1R with CSF-1 recruited M2 macrophages, and its overexpression increased tumor growth, vascularization, and metastasis." (PMID 28197019, 2017). "Based on the widespread use of PD1 and PDL1 inhibitors across tumor entities, a variety of clinical trials combining these agents with CSF1R inhibitors have been initiated." (PMID 28716061, 2017). "As the intratumoral presence of CSF1R+ macrophages correlates with poor survival in various tumor types, targeting CSF1R signaling in tumor-promoting TAM represents an attractive strategy to eliminate or repolarize these cells." (PMID 28716061, 2017). "These include blocking macrophages by inhibiting CSF-1/CSF1R signaling, as well as disrupting cytokines/chemokines that recruit and polarize macrophages to a pro-tumor phenotype." (PMID 28881599, 2017). "Expression of CTLA-4 and CXCR2 was the highest and among the highest for CSF1R expression within the TCGA HNSCC cohort compared to other tumor types." (PMID 28915554, 2017). "Inhibition of TAMs recruitment with CSF-1R inhibitors improves the immune cell response in tumor tissues and enhances the therapeutic efficacy of chemotherapy, radiation therapy and immune checkpoint blockade therapy." (PMID 28848446, 2017). "The addition of a CSF1R inhibitor restored response to anti-angiogenesis therapy, resulting in 83% lower tumor burden compared to treatment with anti-VEGF antibody and paclitaxel alone." (PMID 29228548, 2017). "There, TGFBI (5q31) was reported to be amplified in 70% of ccRCC cases (7/10) with 5q23.2–q34 gain and CSF1R (5q32) to be upregulated in 30% of tumours (3/10)." (PMID 28486536, 2017). "Evidence also suggests that VEGFR, FGF receptors (FGFRs), and colony stimulating factor 1 receptor (CSF1R) promote tumor immune evasion." (PMID 28159938, 2017). "Some other studies find blocking tumor-infiltrating macrophages with CSF1R inhibitor benefits the therapeutic effect of PD1 and CTLA4 antagonists, indicating tumor-associated macrophage (TAM) is a promising tumor therapy target." (PMID 29152078, 2017). "It has been shown that the colony-stimulating factor-1 (CSF-1) and its receptor CSF-1R sustain monocytes/macrophages survival, proliferation, and motility, and also contribute to tumor progression." (PMID 28170411, 2017). "In most studies, anti‐CSF1R antibody‐based therapies were shown to decrease total macrophages population in various tumor models in mice and patients." (PMID 29038312, 2017). "Consistently, the short-term blockade of CSF1R after micrometastasis formation showed negligible effects on the metastatic tumor expansion, although long-term genetic MAM depletion through loss of Csf1 substantially inhibits metastasis." (PMID 29387063, 2017). "In this context, TAM-derived suppressive cytokines such as IL-10 or the general T-cell suppressive functions of TAM provided the basis for increased tumor-inhibitory effects of CSF1R inhibitors combined with immunotherapies." (PMID 28716061, 2017). "Phosphorylation of CSF-1R Y721 enhances tumor cell motility and invasion through the PI3K/AKT pathway." (PMID 29228668, 2017).